GRPEL2 (GrpE like 2, mitochondrial)
Description:
Essential component of the PAM complex, a complex required for the translocation of transit peptide-containing proteins from the inner membrane into the mitochondrial matrix in an ATP-dependent manner. Seems to control the nucleotide-dependent binding of mitochondrial HSP70 to substrate proteins. Stimulates ATPase activity of mt-HSP70. May also serve to modulate the interconversion of oligomeric (inactive) and monomeric (active) forms of mt-HSP70 (By similarity).
Synonyms: DKFZp451C205; Mt-GrpE#2; FLJ23713
Tractability: PROTAC: ubiquitination databases record sites on it; its protein half-life has been measured.
Gene: Protein-coding gene on chromosome 5 (149,345,430 to 149,354,583, forward strand). Ensembl gene ENSG00000164284.
Subcellular location: Mitochondrion matrix
Subcellular location (Human Protein Atlas): Mitochondria
Pathways (Reactome):
Protein localization: Mitochondrial protein import
Gene Ontology:
Molecular function: adenyl-nucleotide exchange factor activity; protein binding; protein homodimerization activity; protein-folding chaperone binding
Biological process: protein import into mitochondrial matrix; intracellular protein transport; protein folding
Cellular component: mitochondrial matrix; mitochondrion; mitochondrial inner membrane; PAM complex, Tim23 associated import motor; TIM23 mitochondrial import inner membrane translocase complex
Genetic constraint (gnomAD): Loss-of-function variants: 15 observed, 18.85 expected, observed/expected ratio (o/e) 0.8, 90% interval 0.53 to 1.23. The upper end of that interval is the gene's LOEUF score, 1.23, which puts it in group 5 of 6, group 1 being the genes least tolerant of losing a copy. Missense variants: 217 observed, 246.59 expected, observed/expected ratio (o/e) 0.88, 90% interval 0.79 to 0.99. Synonymous variants: 98 observed, 102.41 expected, observed/expected ratio (o/e) 0.96, 90% interval 0.81 to 1.13.
Homologues: Orthologues: chimpanzee GRPEL2 (99% identical), macaque GRPEL2 (96% identical), guinea pig GRPEL2 (88% identical), mouse Grpel2 (85% identical), pig GRPEL2 (81% identical), rat Grpel2 (81% identical), zebrafish grpel2 (48% identical), tropical clawed frog grpel2 (46% identical), Drosophila melanogaster Roe1 (34% identical), Caenorhabditis elegans C34C12.8 (30% identical). Paralogues in human: GRPEL1 (40% identical).
Diseases named in the same sentence as GRPEL2 in open-access papers:
GRPEL2 is named in the same sentence as 20 diseases in open-access papers, as found by Europe PMC text mining. Sharing a sentence is not in itself a finding about the gene and the disease. The quoted sentences say what the papers report.
glioma (2 papers, 2021 to 2024). A benign or malignant brain and spinal cord tumor that arises from glial cells (astrocytes, oligodendrocytes, ependymal cells). "Further immunostaining confirmed that an elevated GRPEL2 staining (by immunoscore) significantly correlated with the WHO tumor grade (p < 0.05) and that a greater GRPEL2 staining (by immunoscore) was associated with higher-grade gliomas (WHO 3 to 4, p < 0.05)." (PMID 34884508, 2021). "Utilizing multi-omic functional genomics data associated with glioma phenotypes showed that GRPEL2 mRNA expression was exclusively correlated with oligodendroglial differentiation in the phenotypes of oligodendroglioma (O), anaplastic oligodendroglioma (AO), and GBM in all datasets (p < 0.05)." (PMID 34884508, 2021). "GRPEL2 has been regarded as an auxiliary element in dysregulating mitochondria energy and protein import leading to apoptosis in gliomas." (PMID 34884508, 2021). "The evaluation of cell growth after the GRPEL2 downregulation revealed that the number of glioma cells was significantly lower in siGRPEL2-expressing cells than in control." (PMID 34884508, 2021). "To semi-quantitatively evaluate the GRPEL2 protein expression in human gliomas, we applied microarrayed tissue slides containing various WHO-grade gliomas for immuno-histochemical (IHC) staining." (PMID 34884508, 2021). "Normal (non-neoplastic) brain tissue was stained negatively or was dimly faint for anti-GRPEL2 staining, whereas a greater GRPEL2 intensity was enhanced at higher-grade gliomas." (PMID 34884508, 2021). "In the present study, we investigated and tested the putative role of GRPEL2 participating in gliomas exclusively from TCGA and CGGA screening." (PMID 34884508, 2021). "After the transfection of siGRPEL2 or siRNA (scramble siRNA) into the LN229 and GBM8401 glioma cells, the expression of the GRPEL2 protein was inhibited compared to the control." (PMID 34884508, 2021). "To confirm the role of GRPEL2 on glioma cell growth, we examined LN229 and GBM8401 glioma cell growth by cell counting after GRPEL2 silencing." (PMID 34884508, 2021). "We found that GRPEL2 mRNA expressions and protein were significantly higher in all glioma cell lines, except for the U87 cells, than in healthy brain tissue (p < 0.01)." (PMID 34884508, 2021). "To further investigate GRPEL2 mRNA and protein expression in gliomas, we performed quantitative an RT-PCR and Western blotting of healthy brain tissue in contrast to the U87, LN229, GBM8401, U118MG, and LNZ308 glioma cell lines." (PMID 34884508, 2021). "In this study, we investigated the function of GRPEL2 in glioma." (PMID 34884508, 2021). "This evidence suggests that the GRPEL2 may recruit OPCs in the setting of glioma differentiation, which may be responsible for tumor recurrence and refractoriness to chemotherapy via the redox dysregulation of mitochondria." (PMID 34884508, 2021). "Our preliminary bioinformatics from TCGA and CGGA mining unerringly exhibit that GRPEL2 gene expression correlates with WHO tumor grades (p < 0.001), IDH mutation status (p < 0.001), and overall survival (p < 0.001), and highly correlated with TERT expression in gliomas." (PMID 34884508, 2021). "Overexpression of the genes whose transcripts act as potential targets fordysregulated miRNAs in the IDHmut and IDHwt groups is observed in moreaggressive glioma types: FKBP9 – CREB3L4, MCM4, MCM6, PSMB2, ARID1A, ARL4C, GRPEL2, and C9orf64." (PMID 39539523, 2024). "Our tentative connections between GRPEL2, oligodendroglial differentiation, and IDH status assumed that mitochondrial dysregulation plays a role in wt-IDH gliomas and oligodendroglial- enriched phenotypes." (PMID 34884508, 2021). "Our screening showed that the gliomas with wide-type IDH (wt-IDH), especially in the GBM subtype, exerted an elevated GRPEL2 expression in contrast to IDH mutant (mt-IDH) gliomas and oligodendrogliomas (p < 0.001)." (PMID 34884508, 2021).
cardiac hypertrophy (1 paper, 2023). "Moreover, Grpel2 overexpression attenuated cardiac hypertrophy, interstitial fibrosis and apoptosis in STZ-induced DCM." (PMID 36927450, 2023). "Furthermore, Grpel2 overexpression significantly alleviated heart dysfunction and cardiac remodeling in DCM, including cardiac contractile dysfunction, cardiac diastolic function cardiac hypertrophy, interstitial fibrosis and cardiomyocyte apoptosis." (PMID 36927450, 2023).
diabetes (1 paper, 2023). "In summary, our data indicates that Grpel2 expression is downregulated in the diabetic heart and that cardiac-specific overexpression of Grpel2 alleviates diabetes-induced cardiac contractile and diastolic dysfunction." (PMID 36927450, 2023). "Since pathological myocardial hypertrophy and excess cardiac fibrosis are the most prominent features of DCM, we next explored the potential role of Grpel2 in pathological cardiac remodeling induced by diabetes." (PMID 36927450, 2023). "In the present study, we revealed that Grpel2 overexpression by AAV9-Grpel2 injection alleviated diabetes-induced mitochondrial morphological abnormalities and decreased oxidative stress levels in the diabetic heart in vivo." (PMID 36927450, 2023). "To characterize the effect of diabetes on cardiomyocyte Grpel2 levels in vitro, we also isolated primary neonatal mouse cardiomyocytes (NCMs) and subjected them to high-glucose (30 mmol/l glucose, HG) conditions to mimic diabetes in vivo." (PMID 36927450, 2023). "Furthermore, we explored the underlying transcriptional and molecular mechanisms by which Grpel2 regulates normal mitochondrial bioenergetics, oxidative stress and cardiomyocyte survival in the heart during diabetes." (PMID 36927450, 2023).
diabetic cardiomyopathy (1 paper, 2023). Diabetic cardiomyopathy is a disorder of the heart muscle in people with diabetes. "To gain insight into the role of Grpel2 in the diabetic cardiomyopathy (DCM), we first assessed Grpel2 expression by Western blotting and qRT-PCR analysis in a STZ-induced diabetic mouse model." (PMID 36927450, 2023).
esophageal carcinoma (1 paper, 2022). A primary or metastatic malignant neoplasm involving the esophagus. "GRPEL2 and EZH2 were highly expressed in most cancer types, such as HCC, esophageal carcinoma, and stomach adenocarcinoma." (PMID 36686830, 2022).
glioblastoma (1 paper, 2021). The most malignant astrocytic tumor (WHO grade IV). "GRPEL2 inhibition can decrease survived glioblastoma cells through an oxidative stress-induced cascade and activated the senescence and autophagic flux restoration." (PMID 34884508, 2021). "This work aims to validate the function of GRPEL2 to propose that the dysregulation of mitochondria in energy generation can lead to the apoptosis of glioblastoma cells." (PMID 34884508, 2021). "In summary, we identified an oncometabolic connection between the human GRPEL2 and glioblastoma cell lines." (PMID 34884508, 2021). "However, the role of GRPEL2 in human glioblastoma has yet to be clarified." (PMID 34884508, 2021).
hepatocellular carcinoma (1 paper, 2023). A malignant tumor that arises from hepatocytes. "A previous study reported that Grpel2 ablation significantly increased ROS production and promoted apoptosis by inhibiting the NF-κB pathway in hepatocellular carcinoma." (PMID 36927450, 2023).
ischaemia (1 paper, 2023). "Our previous work indicated that Grpel2 alleviates myocardial ischaemia/reperfusion injury by inhibiting MCU-mediated mitochondrial calcium overload." (PMID 36927450, 2023).
cancer (3 papers, 2021 to 2025). A tumor composed of atypical neoplastic, often pleomorphic cells that invade other tissues. "The gene of GRPEL2 was well verified in the maintaining of mitochondrial homeostasis which is meaningful to several biological process for cancer survival." (PMID 40465781, 2025). "Our putative NEF ortholog, GRPEL2, modulates mitochondrial HSP70′s function in human GBM cell lines, suggesting that GRPEL2 has evolved as a possible anti-tumor hub emerging into modern cancer medicine." (PMID 34884508, 2021). "The pan-cancer analysis results suggest that the eight hub genes (TXNRD1, TUBG1, SF3B4, PPM1G, PIGU, NDRG1, GRPEL2, and EZH2) were differentially expressed in gastrointestinal tumors." (PMID 36686830, 2022).
tumor (3 papers, 2021 to 2025). "It has been proved that the knockdown of GRPEL2 suppressed the growth, invasion and migration in vitro, as well as inhibited the growth of tumor in vivo." (PMID 40465781, 2025). "The multivariate regression analysis showed that EZH2, NDRG1 and GRPEL2, as well as the tumor size were independent factors for the prognosis of HCC." (PMID 36686830, 2022). "This indicated intracellular ROS as another source of oxygen consumption and the anti-tumor effect comprising growth arrest and proliferative retardation can be regulated by GRPEL2 via the ROS level." (PMID 34884508, 2021). "The utilization of LN229 and GBM8401 cells to proceed on GRPEL2 silencing demonstrated a decreased cell growth and inhibited tumor proliferation by ROS-dependent manipulation." (PMID 34884508, 2021). "Fourth, the most applicable strategy is to determine whether the GRPEL2 knockdown enhances the tumor sensitivity to the TMZ frontline chemotherapy, thus exerting cytotoxic synergism." (PMID 34884508, 2021). "We also constructed a prognostic nomogram model, which included EZH2, GRPEL2, NDRG1, and the tumor size." (PMID 36686830, 2022). "EZH2, GRPEL2, NDRG1, and the clinical factor of tumor size, were included in a nomogram for visualizing a prognostic model of HCC." (PMID 36686830, 2022). "The nomogram showed that a larger tumor size and higher EZH2, GRPEL2, and NDRG1expression predicted the higher likelihood of a worse prognosis." (PMID 36686830, 2022). "According to our data set, three genes, EZH2, GRPEL2, and NDRG1, and one clinical factor, tumor size, could be used as reliable indicators for evaluating the prognosis in patients with HCC." (PMID 36686830, 2022). "Therefore, the current research results suggest that EZH2, GRPEL2, NDRG1, and tumor size are reliable prognostic indicators." (PMID 36686830, 2022).
GRPEL2 also shares sentences with these, for which no sentence is quoted: anaplastic oligodendroglioma (1 paper); bladder (1); colon cancers (1); fibrosis (1); gastrointestinal tumors (1); liver cancer (1); malignant glioma (1); oligodendroglioma (1); osteosarcoma (1); stomach adenocarcinoma (1).